MYCN (MYCN proto-oncogene, bHLH transcription factor)
Diseases named in the same sentence as MYCN in open-access papers (continued):
Sharing a sentence is not in itself a finding about the gene and the disease.
neuroblastoma (continued). "However, this was an unusual discordant sample because it was scored as MYCN-amplified by fluorescence in situ hybridization (FISH) in COG’s neuroblastoma reference lab but non-amplified based on normalized read depth from our custom capture Illumina next-generation sequencing data." (PMID 32060267, 2020). "MYCN-amplified retinoblastoma without RB1 mutation appears to have histopathological and genetic characteristics similar to those of other MYCN-amplified embryonic tumors, such as neuroblastoma, even though the tumor features a retinoblastoma-associated gene expression profile." (PMID 33270844, 2020). "To investigate whether MYCN protein regulates CAMKV expression, we transiently depleted MYCN from MYCN amplified IMR-05 cells using shRNA and saw a significant reduction in CAMKV mRNA levels (p < 0.005), suggesting that MYCN is required for CAMKV transcription in MYCN amplified neuroblastoma cells." (PMID 32211329, 2020). "Moreover, although neuroblastoma can evolve to a more aggressive phenotype with mixed numerical (i.e. chromosomal) and segmental (i.e. arm or shorter segments) profile, as seen in Patient 2, this has not been shown to occur in MYCN-amplified neuroblastoma (20–25% of all neuroblastomas)." (PMID 32971811, 2020). "Thus, MYCN, c-MYC, and HDAC8 may each contribute to neuroblastoma tumorigenesis." (PMID 30237861, 2018). "Thus, in neuroblastoma, undifferentiated neuronal cells do not only display typical properties of malignant tumour cells (i.e. absence of neurites and MYCN overexpression); they also express a substantial fraction of shortened and lengthened transcript isoforms compared to a differentiated state." (PMID 30552333, 2018). "We therefor believe that sutent may play anti-self-renewal and anti-malignancy roles in neuroblastoma tumorspheres by inhibiting the protein expression of the stemness-maintenance drivers, SOX2 and PDGFRβ as well as the malignant, proliferative markers MYCN and survivin." (PMID 29298329, 2018). "GANT-61 is an inhibitor of GLI1 and GLI2, known to reduce autophagy in MYCN non-amplified, but not in MYCN amplified neuroblastoma (NB) cells." (PMID 29581853, 2018). "A neuroblastoma-specific panel using NGS could be developed to identify more comprehensive genomic information to molecularly treat and predict prognosis with sophistication based on genomic characteristics such as MYCN, TERT, ATRX, ALK, ARID1, and telomere length." (PMID 28521285, 2017). "High-risk neuroblastoma (HR-NB) includes MYCN-amplified stage 2/3, but reports covering anti-GD2 immunotherapy, which recently became standard for HR-NB, do not provide details on this subset." (PMID 29221128, 2017). "However, there is no biomarker for poor prognosis neuroblastoma without MYCN amplification." (PMID 28862657, 2017). "In the neuroblastoma gene expression dataset linked with the MAQC II research project, the data for 478 tissue samples were present, among them 69 had and 408 did not have MYCN amplification, and for one sample the amplification status was unknown." (PMID 29137381, 2017). "Genome-wide surveys have identified a large number of protein biomarkers, among which v-myc avian myelocytomatosis viral oncogene neuroblastoma derived homolog (MYCN) oncogene, is a strong prognostic marker for advance stage NB, indicating a poor survival rate." (PMID 27517149, 2016). "To reveal the expressional correlation at the mRNA level, we performed qPCR analysis using 87 human NB cDNA samples including all International Neuroblastoma Staging System (INSS) stages with MYCN-amplified and non-amplified tumours." (PMID 27604320, 2016). "However, to our knowledge, these have not yet been utilized to target MYCN in neuroblastoma." (PMID 26771642, 2016). "Importantly, we uncovered a previously unknown mechanism involved in regulation of GLS2 expression in MYCN-amplified neuroblastoma cells, and identified N-Myc as a novel activator selectively upregulating GLS2 (but not GLS1) expression." (PMID 26528759, 2015).
neuroblastoma (continued). "Furthermore, in human neuroblastomas without MYCN amplification, MYCN mRNA expression levels do not correlate with the prognosis of the patients, suggesting that additional events might contribute to the acquisition of increased aggressiveness." (PMID 24391509, 2014). "Understanding the mechanism of suppression at these genes will have important implications with respect to I-BET726 activity in neuroblastoma, as direct inhibition of these genes could potentially reverse the malignant phenotype of 17q alterations even in the absence of MYCN amplification." (PMID 24009722, 2013). "However, some MYCN non amplified (non-MNA) neuroblastomas show poor outcomes as well." (PMID 24065096, 2013). "Alternative strategies more specific to neuroblastoma may involve the direct targeting of the oncogenic miR-17-92 cluster to re-establish DKK3 expression in MYCN amplified neuroblastoma, or the use of agents which directly affect MYCN expression in neuroblastoma cells such as the BET inhibitor, JQ1." (PMID 23226679, 2012). "Here we identify, for the first time, the efficacy of miR-34a in retarding neuroblastoma tumor growth in vivo in both MYCN amplified (NB1691luc) and non-MYCN amplified (SK-N-ASluc) neuroblastoma xenografts; and also propose a potential mechanism through which this might occur." (PMID 21266077, 2011). "Furthermore, whether there are cellular factors limiting for the expression of the MYCN amplicon in neuroblastoma cells has not been investigated in previous studies." (PMID 21304178, 2010). "Through miRNA expression profiling of different genetic subtypes of neuroblastoma, Chen and Stallings and others previously demonstrated that several miRNAs are differentially expressed in these tumors, particularly in regard to MYCN amplified (MNA) versus non-MNA tumor subtypes." (PMID 20409325, 2010). "NB-hypo increases the resolution of the MYCN stratification by dividing patients with MYCN not amplified tumors in good and poor outcome suggesting that hypoxia is associated with the aggressiveness of neuroblastoma tumor independently from MYCN amplification." (PMID 20624283, 2010). "However, in all neuroblastoma samples analyzed, the ratio between MYCN and ΔMYCN expression remains constant and does not correlate with MYCN-amplification or disease stage, indicating that ΔMYCN induced inhibition of MYCN at the protein level is not of relevance in NB." (PMID 19615087, 2009). "However, it appears MYCN is a conditionally favourable gene in neuroblastomas that do not have MYCN amplification and the effect of MYCN expression in neuroblastomas from children of different ages or with disseminated disease may vary." (PMID 18789162, 2008). "Finally, overexpression of miR-17-5p in SH-EP cells (a MYCN-not-amplified neuroblastoma cell line) enhanced cell proliferation through downmodulation of p21, as observed in SK-N-AS cells, thus demonstrating that these effects were not restricted to a particular cell line (data not shown)." (PMID 18493594, 2008). "Thus, although the MYCN expression level itself is not a strong prognostic indicator, MYCN amplification and its attendant increase in MYCN protein remains one of the strongest indicators of the neuroblastoma malignant phenotype." (PMID 18789162, 2008). "Thus, while the upregulation of glycolytic enzymes may be a factor in neuroblastoma malignancy, it may be independent of MYCN expression." (PMID 18789162, 2008). "Thus, current neuroblastoma trials may stratify these advanced stage MYCN non-amplified patients to either the low-, the intermediate- or the high-risk group leading to highly differing treatment approaches." (PMID 17531100, 2007).
neuroblastoma (continued). "However, gene expression data for the important subgroup of MYCN non-amplified neuroblastoma patients of advanced stage disease (International Neuroblastoma Staging System, INSS Stage 3 or 4,) is still rare, leading to a high risk of false positive and false negative findings." (PMID 17531100, 2007). "In human neuroblastoma tissues, high levels of PRKCQ‐AS1, MSI2 or BMX expression predict poor prognosis in MYCN nonamplified but not MYCN‐amplified patients." (PMID 40103284, 2025). "Analysis of published RNA sequencing data from 39 human neuroblastoma cell lines confirms that PRKCQ‐AS1 is overexpressed in MYCN nonamplified, compared with MYCN‐amplified, human neuroblastoma cell lines." (PMID 40103284, 2025). "A major limitation of our in vitro study is that all experimental data are generated in a single neuroblastoma cell line, SH-SY5Y, which is an MYCN-non-amplified NB cell model that represents only low- and intermediate-risk NB." (PMID 41465323, 2025). "In the local cohort, 60 samples (60/90; 67%) classified into neuroblastoma subclasses: 27 samples (27/90; 30%) into TMM negative, 26 samples (26/90; 29%) into MYCN type, and seven samples (7/90; 8%) into “ALT/TERT TMM positive” subclass." (PMID 40713849, 2025). "While ASS1 expression did not correlate with BCT-100 IC50 in neuroblastoma cell lines, upregulation of ASS1/ASL/OTC was observed in some BCT-100 treated Th-MYCN tumors." (PMID 40813699, 2025). "The neuroblastoma cell line NGP demonstrated moderate ALK surface expression (ALK WT, MYCN non-amplified; geometric mean 8.6x IgG control) and there was minimal detection of expression in the NGP ALK KO cell line (geometric mean 1.6x IgG control)." (PMID 40813394, 2025). "Here, we looked for the correlation between the MYCN, CTSD, EGFR and MAPK1 genes and checked the prognostic value of CTSD in the context of MYCN positive and negative neuroblastomas." (PMID 38611021, 2024). "In contrast to effects of AF1q silencing in MYCN amplified neuroblastoma, in SH-SY5Y cells which do not express N-Myc but exhibit high levels of C-Myc expression, silencing AF1q caused no appreciable change in C-Myc levels." (PMID 38413795, 2024). "In neuroblastoma cells with long telomeres (SKNMMMYCN SKNJCIMYCN), induction of MYCN resulted in modest or no increase in MYCN enrichment at the TERT promoter." (PMID 38837897, 2024). "We showed that high level of expression of PHLDA1 positively correlates with survival of MYCN-amplified subset of neuroblastoma patients, but proteins regulated by PHLDA1 exhibit both positive and negative correlation with survival of neuroblastoma patients." (PMID 38495105, 2024). "In tumors without MYCN amplification, MYC is overexpressed, further indicating that neuroblastoma is a MYC-driven cancer." (PMID 38488852, 2024). "To determine if RUNX1T1 is regulated by MYCN, we analysed RUNX1T1 protein and RNA expression in the human SH-EP Tet-21/N cell line, a non-amplified neuroblastoma line with a MYCN doxycycline-off inducible construct." (PMID 38992040, 2024). "These binding profiles are mapped in all three MYCN-amplified (more intensively in LA-N-5 and COG-N-415), but not in non-MYCN-amplified, neuroblastoma cell lines." (PMID 37835497, 2023). "Age of diagnosis, MYCN amplification and 1p deletion were independent prognostic factors of neuroblastoma, while, ZNF436 was not an independent prognostic factor of neuroblastoma in E-MTAB-1781 dataset." (PMID 37904225, 2023).
neuroblastoma (continued). "When DFMO was added to neuroblastoma cell lines as a part of the same study, there was growth inhibition mediated by ODC1 suppression and was observed in cells independent of MYCN amplification." (PMID 37206500, 2023). "The paralog of MYCN, c-MYC, was almost not expressed in our cohort of neuroblastoma patients and thus seemed not to significantly influence circRNA expression." (PMID 37402719, 2023). "MYCN/IGF2BP1 synergy also promotes chromosomal gains at 2p and 17q, but retains strong potential also in non-amplified (2p or 17q) neuroblastoma models, e.g. NBL-S." (PMID 37246217, 2023). "In TARGET, GSE16476 and GSE62564 neuroblastoma cohorts, ROC curves showed the high specificity and sensitivity of ZNF436 in distinguishing MYCN amplified from MYCN non-amplified neuroblastoma patients." (PMID 37904225, 2023). "We showed that miR-323a-3p expression was reduced in advanced stage 4 tumors as compared to stage 1–2 and in MYCN-amplified (MNA) tumors as compared to non-MNA, two well-known prognostic factors of neuroblastoma." (PMID 37033189, 2023). "Neuroblastoma patients with ZNF436 high expressions and without MYCN amplification had significantly longer overall survival in E-MTAB-1781 and TARGET datasets." (PMID 37904225, 2023). "Next, we evaluated the effect of nanospermidine in two neuroblastoma cell lines: NLF (with MYCN amplification) and BR6 (without MYCN amplification, with TrKA expression)." (PMID 35745787, 2022). "Harmine 22 also induced apoptosis in different neuroblastoma cell lines such as SKNBE and KELLY (MYCN amplified) and SKNAS and SKNFI (MYCN non-amplified)." (PMID 35807542, 2022). "E2F3 expression levels were higher in MYCN amplified neuroblastoma patients in TARGET, GSE16476, GSE85047 and E-MTAB-1781 datasets, compared with neuroblastoma patients without MYCN amplification." (PMID 35764946, 2022). "In Stage 4 MYCN amplified neuroblastoma patients, TRPM2 expression did not correlate significantly with outcome, possibly because MYCN itself transcriptionally regulates expression of many oncogenic proteins including FOXM143." (PMID 36446940, 2022). "Of note, among the tested neuroblastoma cell lines, BE2C and NB1691 are MYCN amplified while SKNAS is not." (PMID 36612203, 2022). "One patient with a residual mass of 1.4 cm at 48 weeks of observation underwent excision two months later and pathology confirmed an MYCN amplified neuroblastoma by FISH, with MYCN plasma being negative at diagnosis." (PMID 36011005, 2022). "Here, we show for the first time that in neuroblastoma, iron chelator VLX600 inhibits mitochondrial respiration, decreases expression levels of MYCN/LMO1, and induces an efficient cell death regardless of MYCN status in both 2D and 3D culture conditions." (PMID 35805002, 2022). "AURKA stabilises MYCN via a direct interaction with a protein binding site flanking MYCN's MBI sequence, this stabilisation of MYCN exacerbates its oncogenic functions, and prevents differentiation of neuroblasts in MYCN-driven neuroblastoma (NB) cell lines, leading to aberrant proliferation." (PMID 34195095, 2021). "To investigate the molecular function of KDM6B in neuroblastoma, we performed RNA-seq followed by gene set enrichment analysis (GSEA) after knockdown of KDM6B in MYCN-amplified (BE2C and KELLY) and MYCN-non-amplified cells (SK-N-AS, SK-N-FI)." (PMID 34893606, 2021). "In this study, we found that di-2-pyridylketone 4-cyclohexyl-4-methyl-3-thiosemicarbazone (DpC) potently decreases N-MYC in MYCN-amplified and c-MYC in MYCN-nonamplified neuroblastoma cell lines." (PMID 35008802, 2021). "In MYCN-nonamplified neuroblastomas, high c-MYC levels indicate an identical clinical outcome to that of MYCN-amplified, further proving their functional overlap and establishing c-MYC as a hallmark of an unfavorable course of this cancer type." (PMID 35008802, 2021).
neuroblastoma (continued). "Here, we highlighted a higher CHK1 expression in MNA compared to non-MNA human neuroblastoma, and in SHH-type medulloblastomas compared to normal cerebella, consistent with an increased efficacy of CHK1i in MNA and in MYCN-OE." (PMID 34508175, 2021). "EVs or total cell lysates were prepared from MYCN-amplified (LAN5, Kelly) and non-MYCN-amplified (SH-SY5Y, SH-EP and GIMEN) neuroblastoma cell lines." (PMID 34847775, 2021). "Although the somatic alterations driving TMM’s in the majority of neuroblastoma are well defined, high telomerase expression can occur in the absence of either a TERT translocation or MYCN amplification." (PMID 32375866, 2020). "Previous results showed that PRMT1 regulated MYCN expression in neuroblastoma, and down-regulation of PRMT1 induced the senescence of non-MYCN amplified neuroblastoma cells." (PMID 32593299, 2020). "A striking example of this was demonstrated in studies of neuroblastoma cell lines, in which sensitivity to THZ1 was almost 10-fold greater in cells harboring amplified levels of the MYCN transcription factor compared to those without amplified MYCN." (PMID 32397434, 2020). "We observed that c-MYC (but not MYCN) expression was consistently increased in neuroblastoma cell lines and patient-derived xenografts (PDX) established from clinical samples of PD neuroblastoma." (PMID 32409685, 2020). "Here, we report that intrinsically high MDM2 expression is required for high-level expression of MYCN, but not for expression of MYC, in retinoblastoma, neuroblastoma, small cell lung cancer, and medulloblastoma cells." (PMID 33425720, 2020). "The importance of MYC expression in neuroblastoma is further emphasized by the fact that neuroblastoma without MYCN gene amplification frequently expressed high levels of C-MYC indicating that C-MYC and N-MYC are mutually exclusive in neuroblastoma." (PMID 33585251, 2020). "Of note, MYCN nonamplified cells, such as GI-MEN neuroblastoma cells, do not seem to be as responsive to this treatment as the two MYCN-amplified models." (PMID 33121173, 2020). "Of note, by examining publicly available gene expression datasets, we detected a negative correlation between MYCN and SYK in neuroblastoma." (PMID 30744170, 2019). "Neuroblastoma patients exhibit de novo resistance to many existing ALK inhibitors, and no clinical therapeutics to target MYCN have yet been developed." (PMID 35582571, 2019). "In neuroblastoma, NONO binds to lncUSMycN, a lncRNA transcribed from approximately 14 kb upstream of MYCN TSS, to post-transcriptionally up-regulate the MYCN expression." (PMID 29773901, 2018). "We tested this mRNA signature in expression data of 200 neuroblastoma tumors and could show correlation of high signature score with worse outcome in the global patient cohort, but not in the subset of high-stage tumors without MYCN amplification (data not shown)." (PMID 30504901, 2018). "Survival of patients with MYC family-driven neuroblastomas where the tumors had MYCN protein (+) and/or MYC protein (+) was significantly worse than that of patients with non-MYC family-driven neuroblastomas where both proteins were (−)/(+/−)." (PMID 29464082, 2018). "To assess the importance of eIF4A in MYCN-driven neuroblastomas, we investigated the effects of eIF4A inactivation by BLF1 on cell growth in cell lines with or without MYCN amplification." (PMID 29954071, 2018). "miR-17-5p was induced by MYCN and reciprocally binds to the gene 3′UTR region to downregulate its expression, creating a negative-feedback loop in MYCN-amplified neuroblastoma cell lines." (PMID 29547527, 2018).